RNU6-820P (RNA, U6 small nuclear 820, pseudogene)
Gene: Small nuclear RNA gene on chromosome 9 (68,935,873 to 68,935,979, reverse strand). Ensembl gene ENSG00000207000.
Homologues: Orthologues: chimpanzee U6 (99% identical), macaque U6 (96% identical), rabbit U6 (93% identical). Paralogues in human: RNU6-12P (94% identical), RNU6-13P (94% identical), RNU6-16P (94% identical), RNU6-25P (94% identical), RNU6-31P (94% identical), RNU6-32P (94% identical), RNU6-41P (94% identical), RNU6-1 (93% identical), RNU6-1152P (93% identical), RNU6-15P (93% identical), RNU6-17P (93% identical), RNU6-18P (93% identical), and 1288 more.